HIF1A (hypoxia inducible factor 1 subunit alpha)
Diseases named in the same sentence as HIF1A in open-access papers (continued):
Sharing a sentence is not in itself a finding about the gene and the disease.
neuroblastoma (continued). "Analysing a cohort of 75 high-risk neuroblastoma, we could not observe any correlation between differentiation-related genes and HIF1A expression." (PMID 34557995, 2022). "Therefore, we analysed whether later neuroblastoma diagnosis correlated with increased HIF1A expression." (PMID 34557995, 2022). "While contribution of oxygen–regulated hypoxia-inducible factors, HIF-1α to cell cycle arrest has been observed in a wide spectrum of solid tumors in vitro, our study suggests hERG as another major molecular mediator of hypoxia-induced cell cycle arrest in neuroblastoma cells." (PMID 31017964, 2019). "We found that 2DG was effective in suppressing the growth of both MYCN-amplified SK-N-DZ and MYCN-non-amplified SK-N-AS neuroblastoma xenografts, which was associated with downregulation of HIF-1α, PDK1 and c-Myc, and a reduction in the number of tumor blood vessels." (PMID 26398947, 2015). "The aim of this study was to investigate the effects of hypoxia-inducible factor-1α (HIF-1α) on the proliferation, migration and invasion of neuroblastoma (NB) cells and the mechanisms involved." (PMID 25811359, 2015). "Whether HIF-1α has a role in the metastasis of neuroblastoma cells is yet to be determined." (PMID 24376734, 2013). "Therefore, to identify novel HIF-regulated target genes we developed an inducible expression system to selectively express either HIF-1α or HIF-2α in PC-12 rat pheochromocytoma cells, and performed siRNA-targeted knockdown of endogenous HIF-1α or HIF-2α in neuroblastoma cells." (PMID 22970249, 2012). "In neuroblastoma, the knockdown of RPL35A has been demonstrated to exert negative regulatory control over the ERK pathway, inhibit HIF1α expression and impede aerobic glycolysis." (PMID 40552444, 2025). "Under high-glucose condition, BACE1 is upregulated with increased Aβ production through HIF-1α activation and decreased LXRα expression via the JNK pathway in a ROS-dependent manner in SK-N-MC, a neuroblastoma cell line." (PMID 39594520, 2024). "In line with this reasoning, activation of the ISR by thapsigargin was also sufficient to downregulate c-MYC, HIF-1α, and MCL-1 in neuroblastoma cells already within 1 h of treatment, whereas BCL-2 levels remained unchanged." (PMID 37973789, 2023). "We assessed the impact of JQ-1 on the mRNA and protein expression of HIF-1α and CAIX in three neuroblastoma cell lines." (PMID 36139358, 2022). "Accordingly, we examined the effects of glucose deprivation on the PI3K/Akt survival signaling pathway and its crosstalk with HIF-1α and Ca2+ homeostasis in SH-SY5Y human neuroblastoma cells." (PMID 35163310, 2022). "Using several neuroblastoma cell lines in vitro, we showed that JQ1 inhibited hypoxia-dependent induction of HIF-1α and decreased the expression of the well-known HIF-1α downstream target gene CA9." (PMID 36139358, 2022). "Together with an increased AQP1 expression in migrated tumor cells, we observe an increase of HIF-1α and HIF-2α in the migrated neuroblastoma cells." (PMID 33644043, 2021). "We reported that AZ reduced HIF-1α and tumor-specific, hypoxia-induced upregulation of carbonic anhydrase IX (CAIX) in neuroblastoma cells." (PMID 34316328, 2021). "Hypoxia and especially the two hypoxia-inducible key regulators HIF-1α and HIF-2α have been established to be of importance in neuroblastoma progression and migration." (PMID 33671521, 2021). "This AQP1 expression correlates with a hypoxic profile of these cells with increased HIF-1α and HIF-2α expression, as well as with NMYC and NCAM expression in two out of three neuroblastoma cell lines." (PMID 33467498, 2021). "AQP1 expression correlates with a hypoxic profile of these cells with increased HIF-1α and HIF-2α expression, as well as with NMYC and NCAM expression in two out of three neuroblastoma cell lines." (PMID 33467498, 2021).
neuroblastoma (continued). "In neuroblastoma patient samples, there was a significant correlation between SHMT2 and hypoxia-inducible factor-1 α (HIF-1α), and SHMT2 expression correlated with worse patient prognosis." (PMID 33066813, 2020). "Oxygen-independent regulation of HIF-1α has also been extensively studied in cancer forms other than neuroblastoma, where insulin, epidermal growth factor and VEGF itself can promote HIF-1α expression." (PMID 29032465, 2018). "Subsequently, Jeong and Pack reported that HIF-1α increases β-catenin expression level and action in SH-SY5Y human neuroblastoma cells." (PMID 26765566, 2016). "In neuroblastoma cells expressing HIF-1α and HIF-2α in normoxic levels of oxygen, the HIF-1α protein has been demonstrated to be expressed at a much lower level compared with HIF-2α." (PMID 26622817, 2015). "Compared to standard culture conditions, human neuroblastoma cells grown at 5% oxygen were reported to have elevated levels of HIF-2α only, whereas those grown at 1% oxygen had increased levels of both HIF-1α and HIF-2α." (PMID 23965235, 2013). "Intermittent hypoxia stimulated the levels of HIF-1α and HIF-2 α proteins and enhanced stem-like properties of neuroblastoma cells." (PMID 22363512, 2012). "Combination of TSA and IFN-α not only decreased endothelial cell migration, invasion, and capillary tubule formation but also inhibited expression of VEGF, HIF-1α, and MMP-9 in neuroblastoma cells." (PMID 21876694, 2012). "Hypoxia or overexpression of HIF-1α increases the BACE1 mRNA and protein levels in mouse neuroblastoma N2a cells." (PMID 21541279, 2011). "We observed that N1E-115 cells express both HIF1α and HIF2α, their common target genes VEGF and adrenomedullin as well as several neuroblastoma classical markers including neuropilin-1, neuronal-specific enolase, Id2 and chromogranin A." (PMID 17655754, 2007). "Later, analyses from datasets of tumor gene expression of 88 neuroblastoma samples revealed high expression of both hypoxia-inducible factor-1A (HIF-1α) and hypoxia-inducible factor-2α (HIF-2α) but not HIF-3α16." (PMID 40032892, 2025). "Similarly to our observations, the activation of autophagy by Rap in human SH-SY5Y neuroblastoma cells upregulates the expression of BECN1 and HIF-1α and enhances the protective effect against brain injury." (PMID 39943135, 2025). "In neuroblastoma cells, P2X7 activation promotes HIF-1α level and VEGF secretion by activating PI3K/AKT/GSK3β/MYCN and HIF-1α/VEGF3 signaling pathways, upregulates the expression of HIF-1α and VEGF, and increases intracellular glycogen reserve." (PMID 38273855, 2023). "The over-expression of UTP18 in neuroblastoma promotes the expression of VEGF, Bcl-2, HIF1α, and c-MYC, improves the adaptability of tumor cells to environmental stress, and reduces the death of neuroblastoma cells after exposure to hydrogen peroxide, hypoxia or glucose deprivation." (PMID 35265610, 2022). "For instance, in neuroblastoma (NB), extracellular microenvironment hypoxia is reported to promote extracellular adenosine generation, which induces VEGF production by binding with A3 adenosine receptor and activating HIF-1α/2α/VEGF axis." (PMID 35203627, 2022). "Despite evidence for increased activity of the antioxidant enzymes studied using multiple experimental approaches, we found that HIF1α stability and transcription did not correlate with effects on peroxide levels in neuroblastoma cells and primary neurons." (PMID 34596045, 2021). "The group has also observed that HIF-2α is already stabilized at 5% oxygen in neuroblastoma cells, while HIF-1α is not." (PMID 33467498, 2021). "Further studies in neuroblastoma showed that HIF-2α but not HIF-1α was strongly expressed in well vascularized areas." (PMID 33644043, 2021).
neuroblastoma (continued). "Contrarily, another group demonstrated that although HIF-1α is preferentially expressed in NMYC amplified neuroblastoma cells there is no defined regulatory correlation between these two factors." (PMID 33467498, 2021). "Another study demonstrates that although HIF-1α is preferentially expressed in NMYC amplified neuroblastoma cells there is no defined regulatory correlation between these two factors." (PMID 33644043, 2021). "Similarly, HIF-1α cooperates with BMAL1/MOP3 and CLOCK to regulate gene expression in a cell line of mouse neuroblastoma." (PMID 32823749, 2020). "We investigated the effect BICD1 or BICD2 silencing on HIF1α nuclear translocation in SK-N-MC neuroblastoma cell line as a non-MSC cell model." (PMID 30464225, 2019). "In addition, our data showed HIF-1α, SHH and GLI1 expression levels were related to International Neuroblastoma Staging System (INSS) stages (Spearman rho = 0.415, P < 0.0001; Spearman rho = 0.487, P < 0.0001; Spearman rho = 0.347, P = 0.003)." (PMID 25811359, 2015). "When SH-SY5 neuroblastoma cells were treated with POH-N, significantly (*P<0.02) higher fluorescent signals were detected in cells cultured in hypoxic conditions compared with normoxic conditions in a manner similar to that of HIF-1α protein levels." (PMID 23094105, 2012). "Indeed, targeting oxygen response pathways, such as HIF-1α and HIF-2α, are promising strategies for suppressing neuroblastoma development and improving outcomes of therapies." (PMID 22363512, 2012). "It has also been noted that only HIF2α, and not HIF1α, was upregulated in neuroblastoma cells cultured in 5% oxygen, whereas HIF1α and HIF2α were both upregulated when the oxygen tension was decreased to 1%." (PMID 17537234, 2007). "Thus, it appears that neuroblastoma tumors are able to cope with hypoxic stress largely due to the combinatorial effects of HIF1α and MYCN, rather than to HIF2α expression." (PMID 41118218, 2025). "Induction of HIF2α but not that of HIF1α has been also demonstrated in neuroblastoma cells." (PMID 35740651, 2022). "Although hypoxia-inducible erythropoietin (EPO) gene expression was shown in human neuroblastoma cells, downregulation of Epo mRNA was found in LuM1 aggregates as compared with Colon26 cells, We next examined whether ABCG1 depletion altered HIF-1α levels in tumors." (PMID 30364132, 2018). "As reported and discussed previously, neuroblastoma tissue cells, positive for HIF-1α, are generally not strongly VEGF-positive, which might appear counterintuitive." (PMID 29032465, 2018). "However, there is not a perfect match between expression levels and the individual cells that express HIF-1α and HIF-2α, suggesting additional mechanisms than just hypoxia to be responsible for stabilized HIF-α protein in neuroblastoma tissues (see “HIF-2α and the perivascular neuroblastoma niche”)." (PMID 29032465, 2018). "Also, expression of HIF-2α, but not HIF-1α, has been observed in well oxygenated neuroblastoma tissue." (PMID 20224786, 2010). "In addition, previous studies demonstrate that the AURKA inhibitor alisertib could inhibit the growth of HCC and neuroblastoma in vivo via the AURKA-AKT axis, and PI3K/AKT activation directly influences HIF-1α-regulated glycolytic pathways and accelerates malignant progression." (PMID 41471272, 2025). "Co-induction of SHMT2 by HIF1α and Myc maintains cell growth by balancing the NADPH/NADP+ ratios in neuroblastoma tumors upon lack of oxygen." (PMID 40097394, 2025). "In neuroblastoma cells, ID1 is downregulated in a hypoxic situation, but it is upregulated by HIF-1α in the absence of hypoxia-induced ATF-3." (PMID 27127787, 2016). "Studies comparing HIF protein expression with the expression of hypoxia driven genes at the cellular level in tumor sections have shown that HIF-1α/HIF-2α expression is not always congruent with an expression of established hypoxia driven genes such as TH and IGF-2 in neuroblastoma." (PMID 33467498, 2021).
neuroblastoma (continued). "The mRNA levels of TG2 isoforms, hypoxia-inducible factor (HIF)-1α, p16, cyclin D1 and B1, as well as markers of cell proliferation/death, DNA damage, and cell cycle were examined in SH-SY5Y (non-MYCN-amplified) and IMR-32 (MYCN-amplified) neuroblastoma cells in hypoxia/reoxygenation conditions." (PMID 32085516, 2020).
myocardial infarction (114 papers, 2008 to 2026). Gross necrosis of the myocardium, as a result of interruption of the blood supply to the area, as in coronary thrombosis. "Recent studies have suggested that upregulated HIF-1α activity is closely linked with cardioprotective effects induced by myocardial infarction; the related mechanism promotes angiogenesis and improves metabolism." (PMID 32626732, 2020). "As such, the scavenging of ROS effectively modulates the inflammatory microenvironment and inhibits the proliferation of cardiac fibroblasts by causing the constitutive expression of HIF-1α, thereby suppressing fibrosis and promoting heart repair following myocardial infarction." (PMID 39125400, 2024). "These authors suggested that the reduced activity of the variant form of HIF1A could reduce plaque neovascularization and the risk of intraplaque hemorrhage and of subsequent acute myocardial infarction." (PMID 18980686, 2008). "The actin-sequestering proteins, thymosin beta-4 (Tβ4) and hypoxia-inducible factor (HIF)-1α, are known to be associated with angiogenesis after myocardial infarction (MI)." (PMID 34178995, 2021). "In mice suffering from myocardial infarction (MI), it has been demonstrated that HIF-1α directly increases the expression of TRPC1." (PMID 40533673, 2025). "PHD1 knockout mice exhibit a similar upregulation and stabilization of HIF1α following myocardial infarction as our previous studies with PHD 2 and PHD 3 knockout mice." (PMID 40136672, 2025). "Following myocardial infarction, local hypoxia in the injured tissue stabilizes hypoxia-inducible factor-1α (HIF-1α), which activates the expression of genes related to pro-inflammatory cytokines." (PMID 41583440, 2025). "Under hypoxic conditions, Tβ4 facilitates the formation of new collateral vessels following myocardial infarction by modulating the miR-17-5p/PHD3/Hif-1α signaling pathway (PMC8964820)." (PMID 40070869, 2025). "Combined therapy using HIF-1α gene delivery and MSCs in a myocardial infarction model enhanced angiogenesis and cardiac function compared to monotherapies, possibly due to improved MSC engraftment." (PMID 41303720, 2025). "In myocardial infarction models, Phd2 knockout led to significantly increased HIF-1α and VEGF levels in peri-infarct tissue, leading to enhanced neovascularization, reduced fibrosis, and improved cardiac function." (PMID 41303720, 2025). "In a mouse model of myocardial infarction, constitutive expression of HIF-1α attenuated infarct size, increased capillary density, and improved heart function 4 weeks post- myocardial infarction." (PMID 41303720, 2025). "According to reports, a PHD inhibitor named GSK360A taken orally can protect the ischemic heart following myocardial infarction and increase HIF-1α signaling." (PMID 40136672, 2025). "This is consistent with a previous study showing that upregulation of HIF-1α in acute myocardial infarction can prevent cardiomyocyte apoptosis by increasing the antioxidant response." (PMID 41295364, 2025). "HIF1α, activated by myocardial infarction (MI)/hypoxia, bound to the FTO promoter to decrease its expression, causing aberrant m6A modification, while FTO-mediated m6A modification of EPRS, regulated by IGF2BP3, played a key role in cardiac fibrosis after MI." (PMID 39869517, 2025). "Moreover, influence of FTO on HIF-1α extends beyond cancer, playing a pivotal role in cardiovascular disorders, including ischemic heart disease and myocardial infarction (MI), both of which are associated with hypoxia." (PMID 40102715, 2025). "In a porcine model of acute myocardial infarction, overexpression of HIF-1α resulted in increased myocardial perfusion post-injury." (PMID 41303720, 2025).